MIR200CHG (MIR200C and MIR141 host gene)
Synonyms: U47924.27
Gene: Long non-coding RNA gene on chromosome 12 (6,962,024 to 6,964,458, forward strand). Ensembl gene ENSG00000257084.
Gene Ontology:
Biological process: miRNA-mediated post-transcriptional gene silencing
Cellular component: RISC complex
Diseases named in the same sentence as MIR200CHG in open-access papers:
MIR200CHG is named in the same sentence as 7 diseases in open-access papers, as found by Europe PMC text mining. Sharing a sentence is not in itself a finding about the gene and the disease. The quoted sentences say what the papers report.
breast carcinoma (7 papers, 2021 to 2024). "We found that MIR200CHG is highly expressed in breast cancer tissues and is related to the tumor size and histopathological grade." (PMID 34272387, 2021). "We find that MIR200CHG is significantly upregulated in breast cancer and is related to the tumor size and histopathological grade." (PMID 34272387, 2021). "In summary, we confirm that MIR200CHG is upregulated in breast cancer and is related to the tumor size and histopathological grade." (PMID 34272387, 2021). "LncRNA microarray analysis reveals that lncRNA MIR200CHG is highly expressed in breast cancer tissues compared to the adjacent normal tissues (fold change = 17.042, P = 0.022)." (PMID 34272387, 2021). "In vitro and in vivo experiments confirmed that MIR200CHG can promote breast cancer proliferation, invasion, and drug resistance." (PMID 34272387, 2021). "MIR200CHG promotes breast cancer proliferation, invasion, and treatment resistance." (PMID 38347041, 2024). "However, the expression of MIR200CHG was also found to be heterogeneous in breast cancer cell lines in their study." (PMID 38065939, 2023). "LncRNA MIR200CHG directly binds to YB-1 to inhibit its ubiquitination and degradation, simultaneously increasing YB-1 pS102 expression in the nucleus and cytoplasm to promote proliferation, invasion and drug resistance in breast cancer." (PMID 35406781, 2022). "MIR200CHG can stimulate proliferation, invasion, and drug resistance in breast cancer by interacting with and normalizing YB-1, which is involved in regulating hypoxia-dependent gene transcription, and the hypo-phosphorylation of lactate metabolism related-signaling such as mTOR and HIF1 in cancer." (PMID 35422758, 2022). "In addition, MIR200CHG promotes YB-1 phosphorylation at serine 102 and nuclear translocation, promoting the proliferation, metastasis, and resistance to cisplatin of breast cancer." (PMID 35406781, 2022). "Since MIR200CHG is more highly expressed in luminal A breast cancer and YB-1 is more highly expressed in triple-negative breast cancer, we believe that the endogenous expression of YB-1 in breast cancer is regulated by more other factors." (PMID 34272387, 2021). "Through gain and loss of function and rescue experiments, we confirm that MIR200CHG regulates the expression of tumor-associated proteins CDKN2A, cyclin D1, cyclin E1, BCL2, BAX, MMP1, MMP2, and MRP1 by binding YB-1, thereby promoting breast cancer proliferation, invasion, and resistance." (PMID 34272387, 2021). "Therefore, down-regulating MIR200CHG expression may be an effective way to inhibit breast cancer progression." (PMID 34272387, 2021). "Targeting MIR200CHG may help to overcome the progression and chemotherapy resistance of breast cancer, and provide a new strategy for using lncRNA as a molecular target for breast cancer treatment." (PMID 34272387, 2021). "Therefore, MIR200CHG can promote the proliferation, invasion, and drug resistance of breast cancer by interacting with and stabilizing YB-1, and has the potential to become a target for breast cancer treatment." (PMID 34272387, 2021). "Moreover, MIR200CHG can activate the transcription of multiple tumor-related proteins by regulating the ubiquitination and phosphorylation status of YB-1, thereby promoting the progression of breast cancer." (PMID 34272387, 2021). "We find that MIR200CHG and YB-1 bind stably in breast cancer cells, and the changes in the expression of MIR200CHG do not affect the level of YB-1 mRNA but affect the post translational modification status of YB-1." (PMID 34272387, 2021).
gastric cancer (3 papers, 2023 to 2025). A primary or metastatic malignant neoplasm involving the stomach. "LncRNA-MIR200CHG (U47924.27) is a major regulator of EMT in gastric cancer of the MSS/EMT subtype, inducing a mesenchymal phenotype of gastric cancer cells due to MIR200CHG silencing due to hypermethylation of its promoter." (PMID 40296904, 2025). "Collectively, these findings suggest that MIR200CHG may serve as a biomarker for predicting the disease progression of gastric cancer." (PMID 38065939, 2023). "LncRNA MIR200CHG is another candidate that sponges a microRNA miR-200c, protecting it from degradation and inhibiting EMT downstream while other findings in this regard suggest that MIR200CHG modulates miR-429 further regulating EMT in gastric cancer." (PMID 40176927, 2024).
bladder cancer (1 paper, 2022). "Furthermore, GSE89006 dataset showed a high expression of AL035461, AC008735.2, and MIR200CHG in bladder cancer compared with NATs." (PMID 35992824, 2022).
skin cutaneous melanoma (1 paper, 2021). "Although MIR200CHG is also upregulated in several other cancers, it is downregulated in kidney renal clear cell carcinoma (KIRP), kidney renal papillary cell carcinoma (KIRC), and skin cutaneous melanoma (SKCM), indicating that MIR200CHG may function in a context-dependent manner." (PMID 34272387, 2021).
cancer (4 papers, 2021 to 2024). A tumor composed of atypical neoplastic, often pleomorphic cells that invade other tissues. "Remarkably, co-expression analysis revealed a significant inverse correlation between the promoter methylation and expression of MIR200CHG in 25 cancers." (PMID 38065939, 2023). "Moreover, the univariate Cox regression analysis revealed MIR200CHG as a prognostic indicator in nine cancers, highlighting its broad translational potential, which warrants independent validations in the future." (PMID 38065939, 2023). "Besides, we observed a significant positive correlation between the expression of MIR200CHG and miR-200c in 29 cancers." (PMID 38065939, 2023). "In contrast, a significant inverse correlation was found between the expression of MIR200CHG and ZEB1, a core EMT marker, consistently across 20 cancers, suggesting that the function of MIR200CHG in inhibiting the EMT pathway may represent a general mechanism to suppress cancer metastasis." (PMID 38065939, 2023). "Therefore, the function of MIR200CHG may be cancer tissue-dependent, cancer subtype-dependent and impacted by other factors such as subcellular localization." (PMID 38065939, 2023). "Finally, we investigated MIR200CHG in all 33 cancers in the TCGA database." (PMID 38065939, 2023). "MIR200CHG is the host gene of two intronic miRNAs – miR-200c and miR-141 – members of the miR-200 family, which has been demonstrated to inhibit the EMT pathway in cancer cells by directly repressing the EMT-inducing transcriptional factors ZEB1 and ZEB240." (PMID 38065939, 2023).
tumor (3 papers, 2021 to 2024). "Among the identified lncRNAs, MIR205HG, USP30-AS1, MIR200CHG, and TFAP2A-AS1 were associated with tumor progression, each mediating different processes of tumor development." (PMID 38347041, 2024). "IHC analyses showed that overexpression of MIR200CHG significantly upregulated E-cadherin and downregulated vimentin in primary tumor and LN metastasis in vivo." (PMID 38065939, 2023). "MIR200CHG regulates YB-1 phosphorylation at serine 102, thereby affecting the expression of genes related to tumor cell proliferation, apoptosis, invasion, and drug resistance." (PMID 34272387, 2021). "MIR200CHG affects the ubiquitination and phosphorylation at serine 102 of YB-1 to regulate the expression of genes related to tumor cell proliferation, invasion, and drug resistance." (PMID 34272387, 2021). "The results showed that MIR200CHG was mainly localized in the cytoplasm of tumor cells." (PMID 38065939, 2023).
MIR200CHG also shares sentences with these, for which no sentence is quoted: triple-negative breast carcinoma (1 paper).